PIAS1 (protein inhibitor of activated STAT 1)
Diseases named in the same sentence as PIAS1 in open-access papers (continued):
Sharing a sentence is not in itself a finding about the gene and the disease.
tumor (continued). "Researchers have established that an increase of PIAS1 protein expression influences tumor initiation and progression." (PMID 30545141, 2018). "In these analyses, patients who had higher amount of PIAS1 in tumor nuclei, relative to the tumor cytoplasm (dichotomized at median), had a more favourable DSOS [HR = 0.47, 95% CI: 0.24–0.92, p = 0.028)." (PMID 28493978, 2017). "Determination of tumor volume and weight at the end of the experiment revealed a significant decrease in both parameters in tumors that arose from cells where PIAS1 was depleted." (PMID 25474038, 2014). "Consistently, WNT5A inhibition by shRNA rescued PIAS1 knockdown-mediated suppression of mammosphere and tumor growth in vivo." (PMID 24586797, 2014). "In order to complement our findings in patient tumor samples we next investigated PIAS1 expression in docetaxel resistant PC3 (PC3-DR) and DU145 (DU145-DR) cells." (PMID 25474038, 2014). "Consistently, the knockdown of WNT5A by shRNA1 significantly enhanced the tumor growth of PIAS1 knockdown MDA-MB231 cells in vivo." (PMID 24586797, 2014). "PIAS1 knockdown significantly inhibited the tumor formation of MDA-MB231 cells in both the subcutaneous and the fat pad models, suggesting an important role of PIAS1 in the regulation of breast tumorigenesis." (PMID 24586797, 2014). "Strikingly, PIAS1 knockdown for 6 days using the shPIAS1-3 sequence and 1 μg/ml doxycycline resulted in a significant reduction in cell proliferation and tumor volume of PC3 and PC3-DR onplants in the CAM experiment." (PMID 25474038, 2014). "Even more, 3 out of 7 mice in the PC3 xenograft and 5 out of 7 mice in the PC3-DR xenograft had no detectable tumor mass at the end of the study, demonstrating complete tumor regression upon PIAS1 knockdown." (PMID 25474038, 2014). "PIAS1 may therefore exert anti-tumor effects, in part, by restraining TGF-β-driven immunosuppression." (PMID 40941002, 2025). "Differential gene expression analyses between PIAS1-positive and PIAS1-negative cells revealed cell-type-specific transcriptional signatures that may drive tumor progression and contribute to immune evasion." (PMID 40941002, 2025). "Depending on tumor context, PIAS1 can exhibit either oncogenic or tumor-suppressive functions." (PMID 40941002, 2025). "Future studies should aim to elucidate upstream regulators of PIAS1 and determine whether restoring or enhancing its activity can reinvigorate anti-tumor immunity and sensitize tumors to immunotherapy." (PMID 40941002, 2025). "Incoming signals to PIAS1+ TAMs from tumor cells included elevated MIF–CD74_CD44 and MIF–CD74_CXCR4 interactions, which in this context may promote M1 polarization." (PMID 40941002, 2025). "Our studies suggest that PIAS1 may act as a sensor protein in the nucleus that responds to growth and inflammatory stimuli in the tumor microenvironment to regulate the self-renewal of TICs through epigenetic gene regulation." (PMID 24586797, 2014). "Strikingly, functional data of our in vitro and in vivo studies identify PIAS1 as a crucial factor for tumor cell survival since PIAS1 knockdown resulted in reduced proliferation and tumor growth as well as increased apoptosis in parental and in docetaxel resistant cells." (PMID 25474038, 2014). "Moreover, when patients were grouped according to tumor recurrence after ini-tial treatment by radical prostatectomy, a significantly elevated PIAS1 expression was observed in tissues from individuals who experienced biochemical relapse (defined by rising PSA levels)." (PMID 25474038, 2014). "Furthermore, PIAS1 knockdown leads to increased expression of the cell cycle inhibitor p21 and to reduced Mcl1 levels, thereby resulting in induced apoptosis of parental and docetaxel resistant tumor cells." (PMID 25474038, 2014). "Together, our findings position PIAS1 as a multifunctional regulator of the OSCC TME, restraining both stromal support for tumor progression and immune escape." (PMID 40941002, 2025).
tumor (continued). "In contrast, PIAS1 inhibition leads to reduced SUMOylation, which, through activation of the TGFβ pathway, promotes EMT, increasing tumor cell survival and metastasis." (PMID 40534859, 2025). "This study identifies PIAS1 as a cell-type-specific modulator of the tumor microenvironment (TME) in OSCC, with functional consequences for tumor progression, immune regulation, and clinical outcomes." (PMID 40941002, 2025). "Our study defines PIAS1 as a pivotal regulator of the OSCC tumor microenvironment, linking high stromal expression to improved patient outcomes and coordinated anti-tumor immune signaling." (PMID 40941002, 2025). "Notably, the reduced PIAS1 expression in OSCC may impair these tumor-suppressive pathways." (PMID 40941002, 2025). "The authors suggested that PIAS1 suppresses BC metastasis through the inhibition of TGF-β signaling, that is thought to promote tumor metastasis via the induction of EMT-like behavior in tumor cells at the primary site of tumor formation." (PMID 35465332, 2022). "Screening of 78 benign and 89 malignant patient samples revealed an induced PIAS1 expression with increasing Gleason score (GSC) [low GSC, ≤7 (3 + 4); high GSC, ≥ 7 (4 + 3)] and tumor stage." (PMID 25474038, 2014). "We therefore investigated consequences of PIAS1 down-regulation on PC3 and PC3-DR tumor growth in a CAM assay." (PMID 25474038, 2014). "A majority of studies to date have focused on the role of PIAS1 in tumor cells, and a key but largely unstudied aspect of PIAS1 function is its role within the non-malignant cellular components of the tumor microenvironment (TME)." (PMID 40941002, 2025). "Future studies directly comparing PIAS1 function across HPV-positive and HPV-negative OSCC are warranted to determine whether it operates as a universal regulator of anti-tumor immunity or displays subtype-specific effects." (PMID 40941002, 2025). "PIAS1 is reported to play a crucial role in the proliferation of PCa cells, possibly through regulation of NFκB and STAT1, which are known regulators of cellular proliferation and apoptosis in several tumour models." (PMID 31639157, 2019). "Analysis of several public available arrays revealed that PIAS1 mRNA expression is not changed between begin and malignant tumour areas." (PMID 31639157, 2019). "Furthermore, we establish the ubiquitin E3 ligase BARD1, a tumor suppressor and partner of BRCA1, as an indirect RNF4 target, regulated by PIAS1." (PMID 29180619, 2017). "Moreover, the relationship between the abundance of PIAS1 or its subcellular localization to DSOS held up even in a multivariate model, adjusting for tumor size and lymph node status (HR = 0.46, (95%CI: 0.22–0.95); p = 0.035)." (PMID 28493978, 2017). "Consistently, the transcription of WNT5A and CCND2, but not CCND1, was also elevated in PIAS1 knockdown xenograft tumor samples." (PMID 24586797, 2014). "Strikingly however, PIAS1 knockdown in the shPIAS1-3+dox group resulted in a complete abrogation of tumor growth in both PC3 and PC3-DR xenografts and was furthermore even sufficient to induce partial tumor regression." (PMID 25474038, 2014). "Because TGFβ is thought to promote tumor metastasis via the induction of EMT-like behavior in tumor cells at the primary site of tumor formation, our observations suggest that PIAS1-suppression of tumor metastasis occurs via its ability to inhibit TGFβ-induced EMT." (PMID 25594015, 2014). "The role of PIAS1 as a tumor suppressor or promoter has not been conclusively determined." (PMID 40260915, 2025). "Furthermore, the WB analysis showed that the expression levels of vimentin, PIAS1, P62, cathepsin B and D, SUMO2/3, SUMO1, and CDC42 were lower in the xenograft tumor tissues of Hct116 and LoVo control cells than in the PDCs." (PMID 37833712, 2023).
tumor (continued). "Collectively, our findings suggest that PIAS1 is a novel negative regulator of EMT and reveal that inhibition of the PIAS1-SnoN sumoylation pathway represents a key mechanism by which TGFβ induces EMT, with important implications in normal development and tumor metastasis." (PMID 21103059, 2010). "Inhibited the anti-tumor effect of IFN-γ and up-regulate the expression of negative feedback regulator PIAS1 by activating the JAK/STAT1 pathway." (PMID 39906741, 2024). "Moreover, IL-17 can inhibit the anti-tumor effects of IFN-γ and up-regulate the expression of the negative feedback regulator PIAS1 by activating the JAK/STAT1 pathway, thereby accelerating HCC development." (PMID 39906741, 2024).
infection (8 papers, 2016 to 2025). The state of being infected such as from the introduction of a foreign agent such as serum, vaccine, antigenic substance or organism. "Influenza A virus A/WSN/1933 (WSN, H1N1) infection has been shown to induce the expression of human PIAS1 both in vitro and in vivo." (PMID 41413919, 2025). "Of the genes within these intersecting pathways, 120 were significantly induced in both ΔUL26 infection and TNFα-treated PIAS1 KO cells relative to their respective control conditions." (PMID 38768227, 2024). "PIAS1 inactivation also reduced the plaque size and initiation of infection for ΔUL26 but to a lesser extent (~25%)." (PMID 38768227, 2024). "In contrast, ΔUL26 viral spread was not significantly impacted by the absence of PIAS1, suggesting that the contribution of PIAS1 to infection depends on the presence of UL26." (PMID 38768227, 2024). "We found that all six Pias1+/- mice died of their infection on day 7 or 8, whereas 5 out of 6 wild-type mice survived." (PMID 35377920, 2022). "PIAS1 has also been reported to be involved in the infection course of different viruses, such as Ebola virus (EBOV), Epstein-Barr virus (EBV), Herpes simplex virus 1 (HSV-1), and Vesicular stomatitis virus (VSV)." (PMID 35377920, 2022). "At 30 h post-infection (p.i.), the cell lysates were immunoprecipitated with a mouse anti-NP mAb, and the presence of NP and PIAS1 in the immunoprecipitates was revealed by western blotting." (PMID 35377920, 2022). "Herein, we show that the infection of HCC-derived Huh7.5 cells with HCV promotes upregulation of the protein inhibitor of activated STAT1 (PIAS1)." (PMID 34684276, 2021). "We first revealed the upregulation of PIAS1 expression following infection by HCV, which is in line with data that show an overexpression of this protein in liver biopsies from HCV patients." (PMID 34684276, 2021). "As the infection proceeds, N concentration in the nucleus increases and the N binding to PIAS1 releases more p65." (PMID 31363150, 2019). "During infection, PIAS1 was recruited to sites adjacent to HSV-1 genomes, also in a PIAS1 SIM-dependent manner, where it colocalized with PML-NB constituent proteins and other SUMO-conjugated proteins." (PMID 27099310, 2016). "The relocalization of PIAS1 to nuclear domains that contained infecting HSV-1 genomes was disrupted during infection with wild-type HSV-1 (HSV-1)." (PMID 27099310, 2016). "Under these infection conditions, PIAS1 had a nuclear diffuse distribution similar to that of Daxx (HSV-1)." (PMID 27099310, 2016). "HFt cells infected with wild-type HSV-1 had a continued decrease in PIAS1 protein levels as infection progressed, down to 56% ± 9% of the levels in mock-infected cells by 9 h postinfection (hpi) (P ≤ 0.01)." (PMID 27099310, 2016). "Following infection with herpes simplex virus 1 (HSV-1), PIAS1 is recruited to nuclear sites associated with viral genome entry in a SIM-dependent manner, consistent with the SIM-dependent recruitment mechanisms of other well-characterized PML-NB proteins." (PMID 27099310, 2016). "While both proteins localize to nuclear domains that contain viral DNA throughout infection, PIAS1 is more prominently recruited to domains that contain infecting HSV-1 genomes, while PIAS4 is more prominently recruited into replication compartments." (PMID 27099310, 2016). "Additionally, we find that the inactivation of PIAS1 sensitizes cells to inflammatory stimulation, resulting in an anti-viral transcriptional environment similar to ΔUL26 infection." (PMID 38768227, 2024). "We demonstrated the upregulation of PIAS1 expression following infection by HCV." (PMID 34684276, 2021). "PIAS1-mediated SUMOylation of PB2 inhibits the replication and pathogenesis of influenza A virus at early time points of infection in cells and mice." (PMID 41413919, 2025).
infection (continued). "It restricts the cytokine signaling pathways during infection and antagonizes NF-κB activation by interacting with the protein inhibitor of activated STAT1 (PIAS1), a crucial regulator of STAT and NF-κB transcription factors." (PMID 40788013, 2025). "During ΔUL26 infection, the expression of these ISGs was elevated, but to a lesser extent, suggesting that UL26 is necessary for PIAS1 to fully suppress ISG gene expression during infection." (PMID 38768227, 2024). "We therefore investigated the role of PIAS1 in HCV infection, using a cell culture infection system based on Huh7.5 cells infected with the JFH-1 (Japanese fulminant hepatitis 1) strain." (PMID 34684276, 2021). "The binding domain of N to PIAS1 overlaps NLS, which reveals a novel function of N in the nucleus for NF-κB activation and induction of proinflammatory cytokines during infection." (PMID 31363150, 2019). "During infection with ICP0-null mutant HSV-1, PIAS1 localized to replication compartments, although this localization phenotype was less prominent than that of PIAS4." (PMID 27099310, 2016). "During infection with ICP0-null mutant HSV-1, PIAS1 also relocalized to the nuclear edge that contained infecting viral genomes, which was identified by the localization of PML or Daxx and the HSV-1 DNA-binding protein ICP4 (ΔICP0)." (PMID 27099310, 2016). "During infection with ICP0-null mutant HSV-1, PIAS1 is differentially required for the stable localization of constituent PML-NB proteins at nuclear domains that contain infecting viral genomes." (PMID 27099310, 2016). "Similar results were observed during UL26ΔC infection, SUMO1 and PIAS1 levels were increased." (PMID 38768227, 2024). "PIAS1 inactivation did not impact the total levels of SUMOylation observed during infection, indicating that PIAS1 is not necessary for the global induction of SUMOylation induced by HCMV." (PMID 38768227, 2024). "Taken together, our data demonstrate that PIAS1 and PIAS4 independently contribute toward the intrinsic antiviral immune response to HSV-1 infection as part of a coordinated host response to infection that is ultimately counteracted by the E3 ubiquitin ligase activity of ICP0." (PMID 27099310, 2016). "We found that those CRISPR-targeted cells with decreased ACE2 expression (SMAD4, EP300, and PIAS1) also exhibited a decrease in both the proportion of infected cells by SARS-CoV-2 nucleocapsid protein immunofluorescence and in viral infectivity by TCID50 at 48 hours post-infection." (PMID 35231079, 2022). "As PIAS4 localizes to domains that contain HSV-1 genomes throughout infection, whether or not PIAS1 also accumulates in replication compartments was evaluated." (PMID 27099310, 2016). "Further, in over-expression experiments in the absence of infection, PIAS1 has been found to SUMOylate the HCMV IE2 protein, although the functional consequences during infection were not explored." (PMID 38768227, 2024). "Further, PIAS1 inactivation reduced the production of infectious virions during low MOI infection, but did not appear to affect infection at high MOI." (PMID 38768227, 2024). "Our results indicate that cells lacking PIAS1 are less permissive to HCMV spread and have increased expression of anti-viral genes, similar to what is observed during ΔUL26 infection." (PMID 38768227, 2024). "We explored the UL26-PIAS1 interaction further and found that TurbioID-tagged PIAS1 could biotinylate UL26 in the absence of infection." (PMID 38768227, 2024). "During infection with ICP0-null mutant HSV-1, the depletion of PIAS1 dramatically reduces SUMO1 accumulation at the nuclear edge that contains infecting HSV-1 genomes, suggesting that other SUMO E3 ligases do not efficiently mediate this particular PIAS1 function." (PMID 27099310, 2016).
neurological disorders (4 papers, 2021 to 2024). "However, as far as our knowledge is concerned, the impact of the dysregulation of RAD23B and PIAS1 in the neurological disorders analyzed in our work is still to be determined." (PMID 39727940, 2024).
PIAS1 also shares sentences with these, for which no sentence is quoted: acute pancreatitis (2 papers); ischemia (2); neurodegenerative disease (2); prostate tumors (2); acute monocyte leukemia (1); Arthritis (1); autism spectrum disorder (1); bladder tumor (1); brain tumor (1); cerebral infarction (1); Charcot-Marie-Tooth disease (1); colitis (1); coronary artery disease (1); Flavivirus Infections (1); head and neck cancer (1); hereditary spastic paraplegia (1); invasive ductal carcinoma (1); lymphoma (1); myocardial ischemia (1); Parkinson disease (1); pneumonia (1); rheumatoid arthritis (1); schizophrenia (1); squamous cell carcinoma (1); urothelial carcinoma (1).